RALA (RAS like proto-oncogene A)
Diseases named in the same sentence as RALA in open-access papers (continued):
Sharing a sentence is not in itself a finding about the gene and the disease.
lung carcinoma (7 papers, 2018 to 2024). "Although RalA and RalGEFs are implicated in tumorigenesis, there are few data for RalGPS2 role in lung cancer." (PMID 32802839, 2020). "BQU57, a derivative of RBC8, disrupted the anchorage-independent growth of human lung cancer cells in vitro and substantially inhibited RALA and RALB activity and tumor growth in vivo." (PMID 39272901, 2024). "We confirmed that these cell-biological effects are applicable to lung carcinoma, as overexpressing RalA in H2170 lung carcinoma cells increased Src and Stat3 phosphorylation." (PMID 36632230, 2023). "Third, to further reinforce the findings from Co-IP assays, we also utilized an in situ Duolink proximity ligation assay (PLA) and confirmed the proximal co-localization of FAM3C with RalA in A549 parental and FAM3C_ox lung carcinoma cells." (PMID 36632230, 2023). "To dispel the notion that FAM3C interacts with RalA only at artificially high levels of protein expression, we repeated the experiment with FAM3C-high SKMES-1 lung carcinoma cells and confirmed the endogenous interaction of RalA and FAM3C." (PMID 36632230, 2023). "This was further corroborated by the reciprocal observations that H2170 FAM3C_ox cells expressed higher p-RalA, whereas FAM3C silencing in four FAM3C highly expressed lung cancer cell lines ablated expression of RalA phosphorylation (right)." (PMID 36632230, 2023). "Here, siRNA inhibition of RALA significantly increased apoptosis and necrosis of lung cancer cell line A549 and reduced invasion." (PMID 35626682, 2022). "Experiments performed by Male and colleagues focused on the role of RALA in lung cancer." (PMID 35626682, 2022). "RalB, but not RalA, is required for the contractility-driven invasion of lung cancer cells (A549, K-Ras mutated)." (PMID 30320548, 2018). "RALA and RALB can have redundant roles, such as in KRAS-driven lung carcinoma." (PMID 35626682, 2022).
colorectal cancer (6 papers, 2021 to 2024). A primary or metastatic malignant neoplasm that affects the colon or rectum. "A few of the Top 10 potential proteomic biomarkers revealed in our study have been previously identified as compounds associated with colorectal cancer’s response to RT, including CEACAM5, KHSRP, RALA, and TSPAN8." (PMID 38410100, 2024). "They analyzed 314 patients with colorectal cancer and found that the level of RALA expression in 0/I/II stage of cancer was similar to that in III/IV stage." (PMID 36466919, 2022). "However, in colorectal cancer, the RALs appear to have opposite roles, with stable shRNA knockdown of RALA suppressing and RALB knockdown enhancing anchorage-independent growth in vitro." (PMID 39272901, 2024). "Likewise, in colorectal cancer cell lines, RALA and RALB have antagonistic functions with silencing of RALA decreasing anchorage independent growth while silencing RALB has the opposite effect." (PMID 34118960, 2021). "It was demonstrated that colorectal cancer cell lines have significantly increased GTP-RALA and total RALA expression relative to normal adjacent mucosa." (PMID 35626682, 2022). "Conversely, RALA and RALB can have discrete functions as demonstrated in breast, bladder, and colorectal cancers." (PMID 35626682, 2022). "The data showed that the staging of colorectal cancer was not significantly correlated with the expression of RALA." (PMID 36466919, 2022). "Recently, RALA was shown to function downstream of HER2 in colorectal cancer cell lines, but to date, this pathway has not been explored in breast cancer." (PMID 34118960, 2021).
hepatocellular carcinoma (6 papers, 2012 to 2022). A malignant tumor that arises from hepatocytes. "Our recent studies have provided evidence that RalA is overexpressed in hepatocellular carcinoma (HCC), and may have potential as a tumor biomarker in HCC detection." (PMID 27286458, 2016). "Overall, our results suggested that a novel small-molecule RalA inhibitor with a 6-sulfonylamide-pyrano [2, 3-c]-pyrazole scaffold suppressed autophagy and cell proliferation in hepatocellular carcinoma, and that it has potential for HCC-targeted therapy." (PMID 34869198, 2021).
ovarian carcinoma (5 papers, 2015 to 2024). A malignant neoplasm originating from the surface ovarian epithelium. "The interaction between RCC2 and RalA is implicated in chemoresistance of ovarian cancer." (PMID 33521058, 2020). "Inhibition of RALA greatly reduced ovarian cancer cell growth and invasion in vitro and tumor growth in a mouse model." (PMID 35626682, 2022). "RCC2 play an oncogenic role by promoting proliferation and migration of DDP-resistant ovarian cancer cell lines and inhibiting cell apoptosis by regulating RalA signaling pathway." (PMID 33521058, 2020). "In addition, RCC2 interacts with RalA and regulates RalA signaling pathway, resulting in cisplatin-resistance in ovarian cancer." (PMID 33521058, 2020). "In addition, RCC2 promotes cisplatin-resistance in ovarian cancer by regulating RalA signaling pathway." (PMID 33521058, 2020). "Furthermore, RalA knockdown activates DDP-resistant ovarian cancer apoptosis, which is inhibited by overexpression of RCC2." (PMID 33521058, 2020). "The same group described the involvement of RCC2, an upstream effector of RAL, and RALA in ovarian cancer cell proliferation, migration, and cisplatin resistance." (PMID 35626682, 2022). "A previous study reports that expression level of RCC2, RalA, and RalBP1 is significantly higher in DDP-resistant ovarian cancer cell lines compared to the DDP-sensitive tissues." (PMID 33521058, 2020). "Both RALA and RALB are highly upregulated in ovarian cancer cell lines." (PMID 35626682, 2022).
Obesity (4 papers, 2023 to 2024). Accumulation of substantial excess body fat. "Together, these in vivo and in vitro data suggest that upregulated Drp1 activity in adipose tissue may be an important contributor to mitochondrial dysfunction during obesity and further that RalA deficiency protects mitochondria from excessive fission by increasing Drp1 S637 phosphorylation." (PMID 37398165, 2023). "A recent study revealed a correlation between obesity and the activation of RalA, a small GTPase that plays a role in various cellular activities." (PMID 39337461, 2024). "Together, these observations support the notion that adipocyte RalA activity is constitutively elevated in obesity." (PMID 37398165, 2023). "Taken together, our data suggest that obesity drives RalA expression and GTP binding activity, leading to its association with PP2Aa, which in turn recruits the catalytic subunit PP2Ac to dephosphorylate Drp1 S637." (PMID 37398165, 2023). "What is the mechanism by which RalA mRNA and protein expression are increased and RalGAP is decreased in adipose tissue during obesity?" (PMID 37398165, 2023). "Here, we report a new regulatory axis for the control of mitochondrial morphology and function in the context of obesity involving prolonged activation of the small GTPase RalA." (PMID 37398165, 2023). "We also observe a positive correlation of expression of the RalGEF RGL2 with BMI in adipose tissue of humans with obesity, expected to correspond to a chronic increase in RalA activity." (PMID 37398165, 2023). "Taken together, these data reveal that persistent elevation of RalA in obesity produces mitochondrial dysfunction in white adipocytes, with profound effects on systemic metabolism." (PMID 37398165, 2023). "Targeted deletion of RalA in white adipocytes prevents the obesity-dependent fragmentation of mitochondria and produces mice resistant to HFD-induced weight gain via increased energy expenditure." (PMID 37398165, 2023). "Obesity leads to the activation of RalA, resulting in the dephosphorylation of the Drp1 protein." (PMID 39337461, 2024). "Lastly, we examined whether signal transduction for GLUT4 translocation downstream of RalA is influenced by obesity." (PMID 37511290, 2023). "Additionally, we showed that signal transduction for the regulation of RalA downstream of Rac1 was partially impaired in Lepob/ob mice, whereas signaling downstream of RalA that led to GLUT4 translocation was unaffected by obesity." (PMID 37511290, 2023). "Collectively, signal transduction for the regulation of RalA downstream of Rac1 was partially inhibited in Lepob/ob mice, whereas the regulation of GLUT4 translocation downstream of RalA was not affected by obesity." (PMID 37511290, 2023). "Additionally, the factors leading to increased RalA GTP binding are not known, although this may be a result of reduced RalGAP expression, as well as hyperinsulinemia and chronic elevations in Akt activity seen in obesity." (PMID 37398165, 2023).
chronic myelogenous leukemia (3 papers, 2012 to 2019). "RALA (associated with ENST00000435766) is a GTPase and a downstream signaling molecule of RAS whose overexpression has been shown to result in malignant transformation and progression in chronic myelogenous leukemia." (PMID 30713603, 2019). "Here, we show that RalA GTPase activity is commonly high in chronic myelogenous leukemia (CML) cell lines and patient samples." (PMID 26967392, 2016).
developmental delay (3 papers, 2018 to 2025). "Recently, de novo variants in RALA have been associated with a neurodevelopmental syndrome characterized by intellectual disability (ID), developmental delay (DD), and seizures." (PMID 39918382, 2025). "In this study, we identified two novel de novo missense variants in RALA (c.217G>A p.(Glu73Lys) and c.73G>C p.(Val25Leu)) in patients with developmental delay, epilepsy, and brain abnormalities." (PMID 39918382, 2025). "The clinical presentation of case 2, characterized by hypotonia, feeding difficulties, developmental delay, and distinct facial dysmorphism aligns with the core phenotype for RALA variants." (PMID 39918382, 2025). "In summary, we show that de novo missense variation disrupting the GTP/GDP-binding functions of RALA lead to developmental delay, intellectual disability, and related phenotypes." (PMID 30500825, 2018). "Regarding the disease mechanisms, it is thought that developmental delay is not caused by a simple loss‐of‐function of RALA." (PMID 39918382, 2025). "Loss of function for RALA causes a severe neural tube defect; de novo missense variation disrupting the GTP/GDP-binding functions of RALA lead to developmental delay, intellectual disability, and related phenotypes (Hiatt-Neu-Cooper neurodevelopmental syndrome, MIM# 619311)." (PMID 34828280, 2021). "Several aspects of our results suggest that developmental delay in humans is not caused by a simple loss-of-function of RALA." (PMID 30500825, 2018).
epilepsy (3 papers, 2022 to 2025). A brain disorder characterized by episodes of abnormally increased neuronal discharge resulting in transient episodes of sensory or motor neurological dysfunction, or psychic dysfunction. "In this study, we report two novel patients with neurodevelopmental impairment and epilepsy carrying previously unreported RALA variants." (PMID 39918382, 2025). "RalGAPA1 deficiency leads to increased RalA activity, and human patients with biallelic RALGAPA1 variants display neuromuscular abnormalities that later develop into severe psychomotor disability and early-onset epilepsy (OMIM #618797)." (PMID 37628572, 2023). "Therefore, RALA brain somatic mutation may be one of the pathogenic mechanisms leading to FCD II, which is always related to drug-resistant epilepsy in children." (PMID 35846790, 2022).
Intellectual disability (3 papers, 2018 to 2025). "Since the identification of CDK13, CAMK2B and RALA as syndromic, intellectual disability genes, we assume that the involvement of CDK13, CAMK2B and RALA genes in the deletion of our patient explains the presence and the severity of the intellectual disability." (PMID 34828280, 2021).
non-small cell lung carcinoma (3 papers, 2016 to 2022). A group of at least three distinct histological types of lung cancer, including non-small cell squamous cell carcinoma, adenocarcinoma, and large cell carcinoma. "In a mouse model of Kras-driven non-small cell lung carcinoma, expression of either RalA or RalB is sufficient to drive tumor growth." (PMID 31201267, 2019). "Murine knockout studies have shown an essential role for either RALA or RALB in KRAS driven non-small cell lung cancer cell proliferation." (PMID 27556501, 2016). "Similarly, RALA expression was down-regulated in tumor tissues of LUSC and LUAD, but researchers found that inhibition of the RALA signaling pathway could treat non-small cell lung cancer." (PMID 36466919, 2022).
breast invasive cancer (2 papers, 2021 to 2022). "(a) Kaplan-Meier curve, obtained from TCGA 1097 cohort, showing the survival probability of patients with tumor breast invasive carcinoma having high or low RalA (pvalue: 5.15 e-03; pAdj: 1.35e-01) or RalB (pvalue: 1.77 e-05; pAdj: 5.99e-03) expression levels." (PMID 33404012, 2021).
colon cancer (2 papers, 2015 to 2017). "Increased Ral activity has been reported in human pancreatic, bladder, and colon cancer cell lines and tissues and RalA is required for the tumorigenic growth of many Ras-driven cancer cell lines." (PMID 28513539, 2017). "Our results support the independence of the RALA pathway from the molecular subtypes thereby emphasizing the importance of RALA as an independent factor in colon cancer pathogenesis." (PMID 26033452, 2015).
gastric cancer (2 papers, 2022). A primary or metastatic malignant neoplasm involving the stomach. "In another study, approximately 15% of gastric cancer patients were found to have RALA autoantibodies." (PMID 35626682, 2022). "Studies by Wang and colleagues demonstrated that RALA interacts with RCC2 in SGC-7901 and MGC-803 human gastric cancer cells." (PMID 35626682, 2022). "Loss of RCC2 decreased RALA activity, and inhibition of RALA via the non-specific RAL inhibitor RBC8 reduced proliferation, migration, and invasion of gastric cancer cell lines." (PMID 35626682, 2022).
Insulin resistance (2 papers, 2024 to 2026). Increased resistance towards insulin, that is, diminished effectiveness of insulin in reducing blood glucose levels. "Ras hyperactivation promotes insulin resistance and inflammation via MAPK/PI3K pathways, whereas RalA supports GLUT4 translocation and insulin granule exocytosis." (PMID 42075902, 2026). "Additionally, brown fat develops insulin resistance in HFD mice, accompanied by an overall reduction in RalA activity even before KO." (PMID 38286821, 2024).
liver cirrhosis (2 papers, 2022). "In HCC, the expression level of RALA and the level of RALA autoantibodies in cancer tissues were significantly higher than those in patients with liver cirrhosis or normal tissues." (PMID 36466919, 2022). "Here, RALA expression and RALA autoantibody levels were found to be significantly higher in tissue and sera samples from HCC patients relative to patients with liver cirrhosis or normal controls." (PMID 35626682, 2022).
metastatic disease (2 papers, 2023). "Given these distinct lines of evidences, aberrant FAM3C expression is likely to represent a prognostic biomarker for predicting the risk of developing metastatic disease, and opens an opportunity to investigate RalA inhibitors as potential targeted therapies." (PMID 36632230, 2023).
myeloid leukemia (2 papers, 2014 to 2023). A clonal proliferation of myeloid cells and their precursors in the bone marrow, peripheral blood, and spleen. "Compared to mice in the RalA+/+ group, a significant number of mice in the RalARosa26-Tg/+ group showed expansion of myeloid leukemia cells (Gr-1+/Mac-1+)." (PMID 36923939, 2023). "In addition, we found that RalA and RalB were labeled with anti-AG polyclonal antibody in myeloid leukemia cell lines by using 2D electrophoresis in conjunction with immunoblotting." (PMID 24587105, 2014).
osteosarcoma (2 papers, 2022 to 2023). A usually aggressive malignant bone-forming mesenchymal neoplasm, predominantly affecting adolescents and young adults. "Thus, in the tumor microenvironment of osteosarcoma, the imbalance in RALA expression between osteosarcoma cells and immune cells may be the cause of aggressive tumor progression, which is one of the highlights of this study." (PMID 36817861, 2023). "It is obviously far from enough to provide key molecules for the targeted therapy and immunotherapy of osteosarcoma only through research of RALA." (PMID 36817861, 2023). "Besides this, the cumulative survival analysis indicated that high expression of RALA in immune cells predicts the better prognosis, suggesting that the regulatory effect of RALA on immune cells affected the occurrence and progression of osteosarcoma." (PMID 36817861, 2023). "In osteosarcoma cells, RALA is mainly localized in the plasma membrane." (PMID 36466919, 2022).
overnutrition (2 papers, 2023 to 2024). An imbalanced nutritional status resulting from excessive intake of nutrients. "Unlike what was observed in iWAT, mitochondria in eWAT display a fragmented morphology even in lean mice, with no change observed after HFD or RalA KO, consistent with the overall energy storage function of this depot even without the anabolic pressure of overnutrition." (PMID 37398165, 2023).
pheochromocytoma (2 papers, 2022). "Except for LAML, lung adenocarcinoma (LUAD) and pheochromocytoma and paraganglioma (PCPG), RALA was higher in almost all cancer samples than in normal controls (P<0.001)." (PMID 36466919, 2022). "The human RALA and RALB genes were cloned from a human pheochromocytoma cDNA library." (PMID 35409173, 2022).
prostate tumors (2 papers, 2016 to 2017). "Serial serum samples were available for 20 patients before and after the surgical resection of prostate tumors, and 11 of these 20 patients were found to have positive results for anti-RalA autoantibody." (PMID 27286458, 2016). "To investigate the possible relationship between tumor stage and RalA expression, we analyzed the clinical characteristics of 34 prostate tumor specimens from the same tissue array that had information on pathology grade, clinical stage, and Gleason scores." (PMID 27286458, 2016). "The expression of RalA in prostate tumor tissues was evaluated by immunohistochemistry (IHC) in tumor microarrays." (PMID 27286458, 2016). "However, RALA and PLCγ1 expression were not significantly correlated with other clinical features of the prostate tumors." (PMID 28903407, 2017).
RASopathies (2 papers, 2022). "All three of these RAS proteins have been identified as mutated in RASopathies, along with non-canonical RAS proteins, RIT1, MRAS, RRAS, RRAS2 and RALA." (PMID 35103797, 2022). "CDC42 and RALA are components of a non‐canonical Ras pathway, but neither functional nor clinical data have yet sufficiently classified them as RASopathy genes." (PMID 35266292, 2022).
sarcoma (2 papers, 2022 to 2023). A usually aggressive malignant neoplasm of the soft tissue or bone. "Compared with the normal tissues from GTEx, sarcoma tissues from TCGA showed a higher mRNA expression level of RALA." (PMID 36817861, 2023). "A single-cell sequencing result of sarcoma directly described the lower expression of RALA in different immune cells." (PMID 36817861, 2023). "What is more, the single-cell sequencing data obtained from TISH showed that the mRNA expression level of RALA in immune cells of sarcoma mice was significantly lower than that in stromal cells." (PMID 36817861, 2023).